PQBP1 (polyglutamine binding protein 1)
Description:
Intrinsically disordered protein that acts as a scaffold, and which is involved in different processes, such as pre-mRNA splicing, transcription regulation, innate immunity and neuron development. Interacts with splicing-related factors via the intrinsically disordered region and regulates alternative splicing of target pre-mRNA species. May suppress the ability of POU3F2 to transactivate the DRD1 gene in a POU3F2 dependent manner. Can activate transcription directly or via association with the transcription machinery. May be involved in ATXN1 mutant-induced cell death. The interaction with ATXN1 mutant reduces levels of phosphorylated RNA polymerase II large subunit. Involved in the assembly of cytoplasmic stress granule, possibly by participating in the transport of neuronal RNA granules. Also acts as an innate immune sensor of infection by retroviruses, such as HIV, by detecting the presence of reverse-transcribed DNA in the cytosol. Directly binds retroviral reverse-transcribed DNA in the cytosol and interacts with CGAS, leading to activate the cGAS-STING signaling pathway, triggering type-I interferon production.
Synonyms: Npw38; MRX2; MRX55; MRXS3; MRXS8; RENS1; SHS
Tractability: PROTAC: ubiquitination databases record sites on it; its protein half-life has been measured.
Gene: Protein-coding gene on chromosome X (48,890,197 to 48,903,640, forward strand). Ensembl gene ENSG00000102103.
Subcellular location: Nucleus; Nucleus speckle; Cytoplasmic granule
Subcellular location (Human Protein Atlas): Nuclear speckles; Nucleoplasm; Primary cilium; Basal body; Cytosol; Microtubules
Pathways (Reactome):
Disease: Dengue Virus-Host Interactions
Metabolism of RNA: mRNA Splicing - Major Pathway
Gene Ontology:
Molecular function: double-stranded DNA binding; protein binding; ribonucleoprotein complex binding; DNA binding; transcription coactivator activity
Biological process: activation of innate immune response; alternative mRNA splicing, via spliceosome; cellular response to exogenous dsRNA; defense response to virus; positive regulation of defense response to virus by host; positive regulation of type I interferon production; regulation of RNA splicing; neuron projection development; regulation of DNA-templated transcription; positive regulation of DNA-templated transcription
Cellular component: nuclear speck; nucleoplasm; nucleus; cytoplasm; nuclear body; cytoplasmic stress granule; neuronal ribonucleoprotein granule
Gene-disease validity (ClinGen):
ClinGen rates the evidence that PQBP1 causes each of these diseases.
Renpenning syndrome (X-linked): Definitive. An X-linked syndrome characterized by intellectual deficiency, microcephaly, leanness and mild short stature.
Homologues: Orthologues: chimpanzee PQBP1 (100% identical), macaque PQBP1 (99% identical), guinea pig PQBP1 (95% identical), pig PQBP1 (95% identical), rabbit PQBP1 (92% identical), dog PQBP1 (87% identical), mouse Pqbp1 (87% identical), rat Pqbp1 (86% identical), zebrafish pqbp1 (61% identical), Caenorhabditis elegans pqbp-1.1 (34% identical), tropical clawed frog pqbp1 (34% identical). Paralogues in human: CACTIN (18% identical), MARVELD3 (13% identical).
Diseases named in the same sentence as PQBP1 in open-access papers:
PQBP1 is named in the same sentence as 51 diseases in open-access papers, as found by Europe PMC text mining. Sharing a sentence is not in itself a finding about the gene and the disease. The quoted sentences say what the papers report.
Intellectual disability (16 papers, 2013 to 2026). "A male patient carried a maternally inherited hemizygous variant in PQBP1, presenting with moderate intellectual disability, behavioral stereotypies, and progressive neuropsychiatric decline." (PMID 40558542, 2025). "PQBP1 was a causative gene for intellectual disability, which affected splicing patterns of many synapse‐related genes." (PMID 38934363, 2024). "Consistently, congenital mutations of the human PQBP1 gene cause intellectual disability and microcephaly, and acquired PQBP1 dysfunction causes neuronal synapse loss in Alzheimer’s disease." (PMID 39103492, 2024). "The PQBP1-linked syndromes share common clinical features including microcephaly, intellectual disability (ID), reduced growth, lean body and muscular atrophy." (PMID 39205314, 2024). "Splicing factor polyglutamine binding protein‐1 (PQBP1) is abundantly expressed in the central nervous system during development, and mutations in the gene cause intellectual disability." (PMID 38342602, 2024). "Mutations in the polyglutamine-binding protein 1 (PQBP1) gene have been associated with Renpenning syndrome, an X-linked disorder characterized by intellectual disability, microcephaly, short stature, and specific facial dysmorphism." (PMID 38971314, 2024). "Although the molecular mechanisms have not been completely elucidated, different mutations in distinct domains of PQBP1 are the hallmark of intellectual disability and development impairment resulting in Renpenning syndrome spectrum." (PMID 39205314, 2024). "Mutations of the human PQBP1 gene were shown to cause intellectual disability and other relevant symptoms." (PMID 35682906, 2022). "Kalscheuer and Ropers discovered a genetic linkage between PQBP1 gene mutations at Xp11.23 and the onset of intellectual disability in patients from five of 29 families with syndromic and non-syndromic forms of X-linked mental retardation." (PMID 35682906, 2022). "Hereditary gene mutations of PQBP1 cause intellectual disability, whereas acquired loss of function of PQBP1 contributes to dementia pathology." (PMID 35682906, 2022). "Its expression patterns in NSPCs are related to the symptoms of intellectual disability and microcephaly in PQBP1 gene-mutated patients and its exogenous expression rescued microcephalic phenotypes." (PMID 32560273, 2020). "It has been reported that SOX2 transcriptionally regulates PQBP1, an intellectual disability–microcephaly causative gene, in neural stem progenitor cells (NSPCs)." (PMID 32560273, 2020). "A similar reduction of dendritic spines in 5xFAD AD model mice and the recovery of dendritic spine density by AAV-PQBP1 suggests AD, a neurodegenerative dementia, and PQBP1-linked intellectual disability (ID), a developmental disease, share a common pathology." (PMID 30283027, 2018). "Among the genes with two hits uniquely in cases were three candidate genes linked to autism by a literature-curated database, DMD, SYNE1, and TBL1X and two genes implicated in schizophrenia (GRIK4) and intellectual disability (PQBP1)." (PMID 26185613, 2015). "Because the expression patterns in NSPCs are related to the symptoms of intellectual disability and microcephaly in PQBP1 gene-mutated patients, we investigated the transcriptional regulation of PQBP1 by NSPC-specific transcription factors." (PMID 23874697, 2013). "Furthermore, SF3B1 is involved in adult neurogenesis, acts as a transcription factors and is associated with PQBP1, which is linked to neurodegenerative disorders and intellectual disability, an endophenotype involved in schizophrenia." (PMID 26460480, 2015). "Subsequently, a number of other research groups confirmed the genetic linkage between PQBP1 and intellectual disability." (PMID 35682906, 2022).
Intellectual disability (continued). "SRRM2 deficiency in neurons destabilized polyglutamine binding protein 1 (PQBP1), a causative gene for intellectual disability (ID), greatly affecting the splicing patterns of synapse-related genes, as demonstrated in a newly generated PQBP1-conditional knockout model." (PMID 30283027, 2018).
Renpenning syndrome (12 papers, 2009 to 2026). "Renpenning syndrome is a rare X-linked genetic disorder caused by variants in the PQBP1 gene, but the information about its prenatal presentation is very limited." (PMID 40761308, 2025). "For example, a recent Korean case study identified a novel mutation in the PQBP1(NM_001032381.2) gene, leading to the diagnosis of Renpenning syndrome." (PMID 40761308, 2025). "Mutations in PQBP1 are causative for neurodevelopmental conditions collectively termed as the Renpenning syndrome spectrum." (PMID 39205314, 2024). "This represents an alternative molecular mechanism by which PQBP1 mediates neurite outgrowth and an alternative explanation for the mechanism underlying the pathogenesis of Renpenning syndrome." (PMID 38971314, 2024). "Primary human monocyte-derived DCs from Renpenning syndrome patients who harbor PQBP1 mutations exhibit a significantly reduced innate response to HIV-1 challenge, emphasizing the role of PQBP1 as a proximal innate sensor of HIV-1 infection." (PMID 34196950, 2022). "The mutations in PQBP-1, mostly frameshifts, have deleterious effects that lead to severe cognitive impairment and results in the Renpenning syndrome, a type of X-linked intellectual disability (XLID)." (PMID 33668121, 2021). "Human ID diseases that are linked to PQBP1, such as Renpenning syndrome, Golabi-Ito-Hall syndrome, and Southerland-Haan syndrome, show multiple symptoms, such as microcephaly, short stature, lean body, and small testis." (PMID 23874697, 2013). "Renpenning Syndrome is a rare X-linked genetic disorder caused by variants in the PQBP1 gene." (PMID 40761308, 2025). "Similarly, a case of Renpenning syndrome has been reported in China, which was associated with the PQBP1(NM_001032381.2):c.28C>G (p.Arg10Gly)." (PMID 40761308, 2025). "By applying PVS1 and PM2 criteria, prenatal ultrasound could help detect potentially pathogenic PQBP1 deletions associated with Renpenning syndrome." (PMID 40761308, 2025). "With this mouse model, the researchers showed that PQBP1 may be responsible for the symptoms seen in Renpenning syndrome spectrum patients and the single causative gene of these disorders." (PMID 39205314, 2024). "Given that the Y65C missense mutation in the WW domain of PQBP1 has been identified in patients with Renpenning syndrome, we further examined whether this mutation affects PQBP1/N-WASP interaction." (PMID 38971314, 2024). "Moreover, by assessing Renpenning-syndrome-spectrum-associated PQBP1 mutations, the importance of intact PQBP1 in the innate immune response to HIV-1 has been unraveled." (PMID 39205314, 2024). "Mutations in the PQBP1 gene have been associated with Renpenning syndrome." (PMID 38971314, 2024). "The families carrying PQBP1 mutations were clinically similar to Renpenning syndrome." (PMID 35682906, 2022). "Mutations in the PQBP1 gene have been identified in patients suffering from different disorders, including Sutherland–Haan syndrome, Golabi–Ito–Hall syndrome, Hamel cerebro-palato-cardiac syndrome, Porteous syndrome and MRX55, which are collectively called the Renpenning syndrome spectrum." (PMID 39205314, 2024). "Thus, we tested the phase separation ability of the three proteins, PQBP1 in Renpenning syndrome, HNRNPK in Au-Kline syndrome, and PAX6 in Aniridia." (PMID 38225666, 2024). "The frequency of all PQBP1 gene mutations has not yet been determined, although Renpenning syndrome spectrum is a rare disease (personal communication)." (PMID 35682906, 2022). "In the other PQBP-1 disease (Golabi-Ito-Hall syndrome), dimerisation of PQBP-1 was speculated to be promoted by the missense mutation (Y65C) in the WW domain." (PMID 33668121, 2021). "Subsequently, PQBP1 was identified as a causative gene for a group of mental retardation including Renpenning syndrome, Golabi-Ito-Hall and the Sutherland-Haan syndromes as well as non-symptomatic X-linked mental retardation with no anomaly." (PMID 19119319, 2009).
Renpenning syndrome (continued). "While the role of PQBP1 in the pathogenesis of neurological disorders has not been fully elucidated, many studies have identified functions of PQBP1 that might explain the symptoms appearing in Renpenning syndrome spectrum patients." (PMID 39205314, 2024).
microcephaly (10 papers, 2009 to 2026). A congenital or acquired developmental disorder in which the circumference of the head is smaller than normal for the person's age and sex. "In conclusion, PQBP1 depletion in mice delayed cell cycle time through Apc4 and likely other molecules that were aberrantly transcribed or spliced, which causes microcephaly." (PMID 39205314, 2024). "Examining the role of the underlying genes, we can see that PQBP1 has been associated with microcephaly." (PMID 33936165, 2021). "Human patients with mutations of the PQBP1 gene show mental retardation and microcephaly as major symptoms." (PMID 19119319, 2009). "Because the expression pattern in NSPCs is critical for an understanding of ID and microcephaly inPQBP1 gene-mutated patients and of stem cell-related pathology in neurodegeneration, we investigated the transcriptional regulation of PQBP1 by NSPC-specific transcription factors in this study." (PMID 23874697, 2013). "In addition, PQBP1 expression in NSPCs could be related to microcephaly, which is another phenotype of PQBP1-linked ID patients." (PMID 23874697, 2013). "Conditional knock-out of Pqbp1 in neural stem/progenitor cells in mice reproduces microcephaly and ID." (PMID 30283027, 2018). "PQBP1-cKO mice generated using nestin-Cre have microcephaly and exhibit cognitive dysfunctions." (PMID 35682906, 2022). "Therefore, PQBP1-linked microcephaly is associated with cortical thickness expansion rather than cortical surface expansion." (PMID 35682906, 2022). "Synapsin 1-Cre Pqbp1-cKO mice exhibit cognitive dysfunctions, but not microcephaly." (PMID 35682906, 2022).
Cognitive impairment (6 papers, 2018 to 2024). Abnormal cognition is characterized by deficits in thinking, reasoning, or remembering. "We next investigated whether upregulation of PQBP1 expression could alleviate DS‐associated eEF2 hyperphosphorylation and cognitive impairment." (PMID 38934363, 2024). "Interestingly, our data suggested a role of PQBP1 dysregulation in DS‐associated eEF2 hyperphosphorylation and cognitive deficits." (PMID 38934363, 2024). "PQBP1 supplementation recovered not only synapse morphology but also cognitive impairment in the AD model mice." (PMID 30283027, 2018). "Restoration of PQBP1 expression could rescue AD‐related pathologies and cognitive deficits in mouse models." (PMID 38934363, 2024). "PQBP1 is essential to induce the nuclear translocation of nuclear factor κB (NFκB), NFκB-dependent transcription of inflammation genes, brain inflammation in vivo, and eventually mouse cognitive impairment." (PMID 35632635, 2022). "Here, we showed that SRRM2 phosphorylation at Ser1068 increases at the early stage of AD pathology associated with the translocation of SRRM2 to the cytoplasm, destabilizes the spliceosome component PQBP1, broadly affects RNA splicing of synapse genes, and eventually leads to cognitive impairment." (PMID 30283027, 2018). "Here the authors show that PQBP1 in microglia is important for sensing extrinsic Tau 3 R/4 R proteins and triggers an innate immune response through cGAS and STING resulting in cognitive impairment." (PMID 34782623, 2021).
HIV-1 infection (5 papers, 2020 to 2025). The type species of lentivirus and the etiologic agent of acquired immunodeficiency syndrome (AIDS). "Upon HIV-1 infection, PQBP1 associates with a positively charged arginine-18 ring within the central channel of CA hexamers of the HIV-1 capsid in the cytoplasm." (PMID 39205314, 2024). "This is the prerequisite for efficient interferon-stimulated gene (ISG) induction upon HIV-1 infection, highlighting the importance of PQBP1 as a co-sensor of the cGAS–STING pathway and its emerging role in innate immunity." (PMID 39205314, 2024). "Recently, PQBP1 has been identified as an indispensable cellular factor of a priming event for recognition of HIV-1 infection by the cGAS–STING pathway, accentuating PQBP1’s role in inflammation and in innate immune response regulation." (PMID 39205314, 2024). "Binding of PQBP1 to CA is the first interaction required for the initiation of an innate immune response during HIV-1 infection." (PMID 39205314, 2024). "The phosphorylation enhances the binding of PQBP1 and cGAS and the oligomerization of cGAS, leading to an enhanced innate response upon HIV-1 infection." (PMID 39205314, 2024). "Recent work has suggested that an additional factor, polyglutamine-binding protein 1 (PQBP1), helps to license cGAS activity during HIV-1 infection, through its capacity to link cGAS to the viral capsid." (PMID 38712059, 2024). "Among all of the well characterized cGAS regulators, polyglutamine binding protein-1 (PQBP1) and Non-POU (Pit-Oct-Unc) domain-containing octamer-binding protein (NONO) are the only host factors currently known to specifically regulate cGAS-mediated innate sensing of HIV-1 infection." (PMID 31968566, 2020).
tauopathy (5 papers, 2021 to 2025). Neurodegenerative disorders involving deposition of abnormal tau protein isoforms (tau proteins) in neurons and glial cells in the brain. "Moreover, PQBP1-mediated microglia activation in the context of tauopathies has been reported, highlighting the role of PQBP1 in sensing exogenous pathogenic species and innate immune response in the central nervous system." (PMID 39205314, 2024). "In addition, PQBP1 has been implicated in neurodegenerative diseases, including Alzheimer’s disease (AD), tauopathy, and polyQ diseases, as a common mediator across multiple disease pathologies." (PMID 35682906, 2022). "Likewise, the interaction between aggregated tau protein, another pathological hallmark of AD and tauopathies, and polyglutamine binding protein 1 (PQBP1), a polyglutamine tract amino acid sequence binding protein that is expressed in microglia, has been detected in vivo and in vitro." (PMID 36358573, 2022). "If PQBP1 deficiency in microglia is similarly safe for human patients, especially under the risk of infection, PQBP1 in microglia could be a target of therapeutics against AD, tauopathy, and other neurodegenerative diseases." (PMID 34782623, 2021). "The vicious circle generated by activated microglia and damaged neurons based on critical molecules, including LRP1, TREM2, and PQBP1, would definitely contribute to AD and tauopathy pathologies and would be critical therapeutic targets." (PMID 34782623, 2021). "As discussed in this review, PQBP1-mediated neurodegeneration could be hypothesized in tauopathies such as AD, FTDP-17, PiD, PSP and CBD." (PMID 39205314, 2024). "Monomeric tau activates the PQBP1-cGAS-STING pathway in microglia, promoting brain inflammation, and can trigger the microglial NF-κB mechanism, driving tau propagation in mouse models of tauopathy." (PMID 38900367, 2025).
Huntington disease (4 papers, 2018 to 2024). Huntington disease (HD) is a rare neurodegenerative disorder of the central nervous system characterized by unwanted choreatic movements, behavioral and psychiatric disturbances and dementia. "PQBP1 was also identified interacting with the causative proteins of polyQ diseases such as Huntington’s disease, Kennedy’s disease and spinocerebellar ataxia, as well as with tau proteins, thereby suggesting a role for PQBP1 in neurodegenerative disorders." (PMID 39205314, 2024). "Indeed, PQBP1 can bind to a number of causative disease proteins, such as mutated huntingtin associated with Huntington’s disease as well as the mutated androgen receptor that is associated with Kennedy’s disease." (PMID 39205314, 2024). "PQBP1 interacts with Htt, the causative gene product of Huntington’s disease, which suggests that these polyQ proteins induce abnormal changes in mRNA transcription and splicing related to synapse functions, similarly to the PQBP1 deficiency in cKO mice." (PMID 35682906, 2022).